CSF1 (colony stimulating factor 1)
Diseases named in the same sentence as CSF1 in open-access papers (continued):
Sharing a sentence is not in itself a finding about the gene and the disease.
tumor (continued). "When anti-CSF1 treatment was combined with anti-PD-1/anti-CTLA4 immunotherapy with gemcitabine chemotherapy they observed complete tumor regression in 30% of mice and an average tumor regression of 85%." (PMID 27886105, 2016). "CSF1 immunostaining positivity was not statistically correlated with the number of giant cells, tumor volume, gender, age, or tumor localization." (PMID 25854167, 2015). "The results showing the presence of a hyperphosphorylated CSF1R protein in cHL cases highlight the importance of CSF1/CSF1R signalling in the recruitment of TAMs, and the importance of this pathway in the reciprocal crosstalk between tumour HRS cells and the microenvironment." (PMID 26066800, 2015). "Depletion of macrophages by genetic ablation of CSF-1 in the MMTV-PyMT mammary tumor model reduces metastasis formation without affecting primary tumor growth." (PMID 26500653, 2015). "It needs to remind that other pathways, such as CSF1/CSF1R, may also be involved in macrophage mobilization as demonstrated in other tumor models." (PMID 23940516, 2013). "Conversely, overexpression of the CSF-1 transgene in the mammary epithelium was found to promote the recruitment of monocyte/macrophages, which correlated with accelerated tumor progression in MMTV-PyMT mice in comparison to the nontransgenic counterparts." (PMID 24314323, 2013). "Cancer cells recruit monocytes, macrophages and other inflammatory cells by producing abundant chemoattractants and growth factors, such as macrophage colony-stimulating factor (M-CSF/CSF-1) and monocyte chemoattractant protein-1 (MCP-1/CCL2), to promote tumor growth and dissemination." (PMID 23549262, 2013). "TAM density was not depleted in the thyroid of one Tg-Braf/Csf-1−/− mouse, which exhibited a tumor weight and histological phenotype comparable to that of control PTCs (data not shown)." (PMID 23372702, 2013). "In our studies, BALF CSF-1 levels were nearly undetectable while IL-1β levels were significantly higher in tumor-bearing lungs vs. naïve (data not shown)." (PMID 21699731, 2011). "Five mouse-specific cytokines were significantly (P=0.03) higher expressed in VEGFA165 tumours compared with control tumours: interleukin 5 (IL5), IL7, chemokine (C-X-C motif) ligand 9 (CXCL9, MIG), colony-stimulating factor 1 (macrophage) (MCSF) and interferonγ (IFNG)." (PMID 22045186, 2011). "Previous studies in PyMT mice illustrate the contribution of the microenvironment to metastatic potential and describe a paracrine loop whereby invasion, intravasation and metastasis involve signaling between macrophages and tumor cells where these cells secrete EGF and CSF1 respectively." (PMID 21108830, 2010). "This indicated that the effect of CSF-1 depletion was not due to a direct effect of CSF-1 on the tumor cells themselves but indicates that both metastatic seeding and persistent growth of tumor cells are dependent on macrophages." (PMID 19668347, 2009). "Macrophages are recruited to the tumor microenvironment by growth factors and chemokines, such as CSF-1, TGF-β, and MCP-1 produced by the tumor cells themselves or cells of the microenvironment, similar to those expressed upon challenge by pathogens or wounding." (PMID 19536297, 2009). "CSF-1 could affect the proliferation of CSF-1R-expressing cells and promote M2 polarization of macrophages.761,1078 pIL-12 + PLX@cR-PssPD could disintegrate at the tumor site and release CSF-1R inhibitor PLX3397 (PLX) and pIL-12." (PMID 40055311, 2025). "The complexity of the tumor microenvironment-especially the CSF-1 secreted by tumor cells-may regulate the activity of NKG2D-positive NK and T cells, with CSF-1-induced RAE-1d expression potentially enhancing these immune cells’ recognition and response to tumor cells." (PMID 41301424, 2025).
tumor (continued). "Whether this reveals different effects of inhibiting CSF-1R compared with decreasing CSF-1 in the tumor, or whether the lack of IGF-1 upregulation reflects a limitation of our athymic model due to lack of T-cell signaling, remains to be investigated." (PMID 40844085, 2025). "For instance, substances such as succinate, histamine, CSF1, E3 ubiquitin protein ligase COP1, and β-glucosylceramide released by cancer cells can modulate metabolic state and induce ER stress of TAMs, thereby escalating the generation of pro-tumor TAMs 58, 101-105." (PMID 40083710, 2025). "Acute blockade of tumor-derived CSF-1 did not affect overall macrophage density." (PMID 40646332, 2025). "In addition, CSF1 has been shown to not only promote TAM polarization towards the M2 phenotype but also induce cell survival and tumor proliferation via an autocrine mechanism, likely further explaining its correlation with high tumor grade." (PMID 38893093, 2024). "Another study, which used CRISPR-Cas9 CSF-1 knockout murine breast (4T1) and colon (MC38) carcinoma models, showed that the inhibition of CSF-1R signaling boosts an immune-permissive TME, and results in improved tumor control compared to mice with parental tumors." (PMID 39457693, 2024). "Importantly, colony stimulating factor 1 (CSF1) has been shown to be important for maintaining TRM populations in PDAC, which are pro‐fibrotic and pro‐tumour, and may be responsible for therapeutic resistance to standard of care chemotherapy gemcitabine." (PMID 38426634, 2024). "In addition, IL-4 induces the expression of VEGF receptor 1/Flt1, which regulates inflammatory response genes, including colony-stimulating factor 1 (CSF1), a master regulator of macrophage functions, in response to VEGFA and increases vascular permeability and tumor cell intravasation." (PMID 39402303, 2024). "Therefore, the inhibition of the CSF-1 or EGF signaling pathway may have promise to disrupt the migration of both cell types and reduce the number of circulating tumor cells (CTCs)." (PMID 39003350, 2024). "In response to colony-stimulating factor 1 (CSF-1), SHP2 binds to the CSF receptor (CSF-1R) complex on the inner membrane of TAMs, thereby activating the RAS/ERK signaling cascade, and in consequence indirectly promoting tumor cell migration, survival, and proliferation." (PMID 38504984, 2024). "Additionally, in situ hybridization analysis in a set of LMS cases demonstrated that LMS cells produced both CSF-1 and CSF-1R, while macrophages did not secrete CSF-1, indicating an autocrine receptor activation at the tumor cell membrane." (PMID 38254773, 2024). "The recruitment of TAMs to the tumoral area is dependent on immunomodulation exerted by tumor cells, which is mostly dependent on the chemokine (C-C motif) ligand 2 (CCL2), vascular endothelial growth factor (VEGF), platelet-derived growth factor (PDGF), and CSF-1." (PMID 39457693, 2024). "CSCs are crucial for monocyte recruitment across tumor types; supernatants from cholangiocarcinoma, hepatocellular carcinoma, or glioblastoma cells under CSC-enriched conditions show elevated levels of tumorigenic macrophage factors like CCL2, CCL5, CSF1, GDF15, IL-13, TGFβ, periostin, and WISP1." (PMID 39068459, 2024). "In addition to CSF1 and IL-4-mediated TAM reprogramming, the chemokine CXCL16 released from tumor cells has also been shown to bind to CXCR6 on microglia cells and drive them toward a pro-tumor phenotype." (PMID 38254796, 2024). "Studies in other tumor types have identified various molecules found in the TME and expressed by tumor cells that inhibit DC activation and drive DCs toward an immunosuppressive, regulatory phenotype, including vascular endothelial growth factor (VEGF), prostaglandin E2 (PGE2), IL-10, and CSF-1." (PMID 38254796, 2024). "Hence, targeting the CSF1/CSF1R could potentially decrease MDSC expansion and activity in the 4T1 tumor model, resulting in enhanced efficacy of therapeutic cancer vaccines." (PMID 37505292, 2023).
tumor (continued). "The colony-stimulating factor-1 (CSF1) and chemokine (C-C motif) ligand 2 (CCL2) are two major promoters for macrophage recruitment in the TME, while hypoxia can also induce the production of CSF1 and CCL2 by tumor cells, leading to the downregulation of the corresponding receptors." (PMID 37445721, 2023). "Therefore, as CSF1 and FGF signals are both involved in the accumulation of tumor- promoting M2 macrophages, MDSCs, and Tregs, the dual inhibition of CSF1R and FGFR1 by sulfatinib may be more effective for cancer therapy than selective CSF1R inhibition." (PMID 37361567, 2023). "Tumor-derived factors such as colony-stimulating factor 1 (CSF1; also known as M-CSF), granulocyte-macrophage colony-stimulating factor (GM-CSF), CC-chemokine ligand 2 (CCL2), CCL7 (or MCP-3), GDNF, IL-33, CXCL12 (SDF-1) and EGF are responsible for myeloid cell recruitment and promote tumor growth." (PMID 36140392, 2022). "However, in advanced tumors, anti-inflammatory mediators released in the TME, such as CSF-1, CCL2, IL13, IL4, IL10, and prostaglandin E2 (PGE2), can revert the anti-tumor program and favor a switch of TAM into an M2 phenotype with pro-tumor and immunosuppressive functions." (PMID 35163420, 2022). "Antibodies designed to broadly deplete TAMs, such as CCL2/CCR2 and CSF-1/CSF1-R neutralising mAbs have performed poorly in the clinic as single agents, characterised by both a lack of effect on specific pro-tumoural subsets and collateral inhibition of anti-tumour TAM activity." (PMID 35020853, 2022). "MTSGCT showed CSF1 split signals in 2% of tumor cells and so no CSF1 rearrangement." (PMID 36320082, 2022). "CSF1 was reported for recruitment and polarization of TAMs in several cancers, and receptor inhibition of CSF1 in GBM could block TAMs from M2-type polarization and inhibit tumor progression." (PMID 35669791, 2022). "It is worthwhile noting that a large panel of cytokines including MCP-1, M-CSF (CSF-1), IL-3, IL-10, IL-12, IL-16, MIP-1β, RANTES, TNF-α and TGF-β2 were upregulated resulting from autocrine effect in POSTN-overexpressing SKOV3 cells leading to potent enrichment of TAMs in the tumor microenvironment." (PMID 36550569, 2022). "CSF-1 forced expression is a cytokine engineering strategy which could improve both CAR-T cell effector function (i.e. persistence/proliferation and cytokine production) and CAR-T chemotaxis to the tumor site." (PMID 35211124, 2022). "The infiltration of TAMs in tumors was mediated by numerous chemotactic factors produced by tumor cells and TME cells including C-C motif ligand 2 (CCL2), CX3C chemokine ligand 1 (CX3CL1), stromal cell-derived factor-1 (SDF-1), colony-stimulating factor-1 (CSF-1) and periostin (POSTN) etc." (PMID 34108959, 2021). "Interestingly, although hypoxia prevents the infiltration of T cells, it stimulates tumor cells to release a large number of macrophage-recruiting factors, such as CCL2, CSF-1, and VEGF, resulting in pronounced enrichment of macrophages in hypoxic tumor regions." (PMID 35070992, 2021). "In addition to CSF1/CSF1R blockade, macrophage reprogramming using HDAC inhibitors or agonistic anti-CD40 antibodies increases the expression of PD-L1 on macrophages, which limits the anti-tumor effect of reprogrammed TAMs." (PMID 34248982, 2021). "Furthermore, CSF1 mRNA was significantly overexpressed in aggressive (blastoid/pleomorphic) MCL subtypes and related to proliferation in tissues), suggesting a relationship between the MCL/macrophages interplay and tumor aggressiveness." (PMID 35008305, 2021). "However, in clinical practice, a lack of evidence on tumor control has limited the use of the combination of CSF1/CSF1R blockade and PD-L1/PD-1 monoclonal antibody to treat solid tumors." (PMID 34248982, 2021).
tumor (continued). "In HCC tumor microenvironment, several cytokines and chemokines such as CXCL1, CSF1, CCL2, CCL9, IL-6, and IL-18 etc., which were secreted from either HCC cells or immune cells, promotes the recruitment and infiltration of MDSCs from the bone marrow into HCC tumor site 32-34." (PMID 33897880, 2021). "However, unlike human CRC, the senescent tumor cells did not secrete CSF1 in AOM/DSS‐induced mouse CRC." (PMID 33643790, 2021). "Once immune cells were recruited to the tumor lesions, macrophages are extraordinarily abundant and are present in all stages of cancer progression under a gradient of tumor-derived chemo-attractants including CCL-2, tumor necrosis factor (TNF), IL-8, IL-6, VEGF-A, and CSF-1." (PMID 34138315, 2021). "Preclinical studies revealed that colony-stimulating factor-1 (CSF1) and receptor (CSF1R) blockade not only decreases the number of the immunosuppressive TAMs, but also reprograms the remaining ones to support antigen presentation and bolster T cell activation within the tumor microenvironment." (PMID 33672917, 2021). "Future studies should examine whether CSF1/CSF1R acts synergistically with CD4+ Th1 cells to activate anti-tumor CD68+ macrophages, or adaptive CSF1 secretion upon exposure to CD4+ T cell-derived cytokines act detrimentally to recruit M2-like TAMs and consequently hamper antitumor immune responses." (PMID 32850346, 2020). "Similarly, in MMTV-Neu transgenic mice, inhibiting the CSF1/CSF1R pathway by a CSF1 inhibitor named GW2580 led to a noticeable decrease of TAMs infiltration in tumor tissue." (PMID 32161718, 2020). "Macrophages are recruited at TME, in response to the secretion by tumor cells and other TME cell types, of a number of chemoattractant soluble factors, including vascular-endothelial growth factor A (VEGF-A), chemokine ligand 2 (CCL2), and colony-stimulating factor 1 (CSF-1)." (PMID 32878276, 2020). "Therefore, the effects of NHWD-870 on CSF1 could affect the ability of the macrophages to proliferate and to secret EGF, which is required for optimal growth of tumor cells." (PMID 32286255, 2020). "Interestingly, the absence of CSF1 did not have a direct effect on tumor growth in the primary setting, but it did show a delay in the formation of lung metastases." (PMID 33374595, 2020). "Experimental stimulation of cells with epidermal growth factor (EGF) or CSF-1 determined simultaneous migration of both tumor cells and macrophages even in the case that only macrophages express the receptor for CSF-1 and the receptor of EGF is present strictly in tumor cells." (PMID 32477352, 2020). "M2 macrophages participate in tumor growth by releasing proangiogenic cytokines and growth factors, e.g. Epidermal Growth Factor (EGF), Vascular Endothelial Growth Factor (VEGF), Platelet-Derived Growth Factor (PDGF), Colony Stimulating Factor-1 (CSF-1), and basic Fibroblast Growth Factor (βFGF)." (PMID 31480382, 2019). "Furthermore, the inhibition of colony-stimulating factor 1 (CSF1)/CSF1 receptor (CSF1R) signaling can functionally block tumor-infiltrating MDSCs enhancing anti-tumor T cell responses and sensitizes IDO-expressing tumors to ICB in various tumor models." (PMID 30898166, 2019). "Several studies have described the presence of other chemokines within the tumor microenvironment (TME), including CCL3, CCL4, CCL5, CXCL12, and growth factors such as colony stimulating factor-1 (CSF1), which may also contribute to monocyte recruitment to tumors." (PMID 31447834, 2019). "However, targeting CSF-1/CSF1-R axis could also lead to compensatory effects, which translate to enhanced tumour progression." (PMID 31331034, 2019). "Various molecules found in the TME and expressed by tumor cells inhibit DC activation and drive DCs toward a suppressive, or regulatory phenotype including vascular endothelial growth factor (VEGF), PGE2, IL-10, and macrophage colony stimulating factor 1 (CSF-1)." (PMID 30991681, 2019).
tumor (continued). "In summary, TAM homeostasis within the MC38 tumor microenvironment is maintained by production of CSF1, not IL34, and inhibition of signaling not only influenced the myeloid compartment but also inhibited CD4+ T cell accumulation, favoring a reduction in CD4+ FoxP3+ T cells." (PMID 31552020, 2019). "In addition, treatment with anti-CSF1 did not lead to a more favorable macrophage polarization (cytotoxic M1 vs. tumor supportive M2 ratio remained unchanged)." (PMID 31214202, 2019). "Furthermore, a number of agents, such as CCL2 inhibitor bindarit, anti-CCL2 mAb carlumab, CSF1 inhibitor GW2580, and dequalinium-14, have been confirmed of potent and sustained anti-tumor activities via declining macrophages infiltration in a battery of cell lines and xenograft models." (PMID 31300030, 2019). "Conversely, the genetic overexpression of Csf1 in the mammary epithelium of MMTV-PyMT mice results in the premature accumulation of macrophages around hyperplastic lesions and adenomas and accelerates both the development of an angiogenic vasculature and tumor progression." (PMID 29766399, 2018). "Furthermore, treatment with neutralising anti-CSF-1R or anti-CSF1 antibodies can lead to a compensatory increase in granulocyte colony stimulating factor (CSF3), which stimulates an increase in neutrophils at the primary tumour site and in metastatic deposits." (PMID 28210073, 2017). "When compared to differentiated tumor cells, the GSCs show an increased capacity in active chemoattraction and recruitment of TAMs, processes mediated by chemokines and growth factors, secreted by GSCs, including VEGF, neurotensin, SDF1, and soluble colony-stimulating factor 1 (sCSF-1)." (PMID 26977157, 2016). "Indeed, this idea has recently been supported by experimental studies in mouse models for glioblastoma and pancreatic cancer showing that CSF-1/CSF-1R pathway blockade can shift TAM polarization toward an anti-tumor phenotype, resulting in enhanced CD8+ T cell-mediated anti-tumor immunity." (PMID 26500653, 2015). "Lack of both Vav1 and CSF1 correlated with lower tumor grade (p<0.05)." (PMID 25313137, 2014). "In the PyMT spontaneous tumor model used in our study, the anti-CD115 mAb by itself could efficiently reduce tumor growth, suggesting that targeting the receptor might have a superior therapeutic effect than blocking CSF-1." (PMID 24019914, 2013). "Although both CSF-1 and CCL-2 can be targeted to the tumour cells themselves, the strong correlation of overexpression of these macrophage chemoattractants with macrophage recruitment and poor prognosis suggests that TAMs can play a major role in the progression of tumours to metastasis." (PMID 15164120, 2004). "The increased expression of CXCL12 and CSF1 in senescent CRC tumor cells establishes a cytokine barrier that suppresses immune infiltration by tumor-associated T cells, thereby protecting non-senescent tumor cells from immune attack and promoting resistance to CRC." (PMID 40896432, 2025). "Secreted cytokines (MIF/CSF1) mainly target C1QC+TAMs to impede the antitumor immune effects of TAMs rather than those of SPP1+TAMs, suggesting that anti-CSF or MIF treatments may be insufficient to deplete macrophage subgroups with tumor growth-promoting potential." (PMID 39323622, 2024). "However, we could not investigate the involvement of macrophages in tumor invasion in Apc/Dok3 mice, because we failed in our attempt to breed mice lacking Dok-3 and Csf1, the latter of which is critical for development of macrophages." (PMID 36970719, 2022). "Based on the negative association between CSF-1 and infiltration of CD8+ T cells, we assumed that CSF-1 is a critical factor in regulating the CSF-1R+CD11c+ MDSC cells in the TME and can thus prevent tumor elimination mediated by the trametinib/αPD-1 combination." (PMID 35292516, 2022).